ROBO3 (roundabout guidance receptor 3)
Description:
Receptor involved in axon guidance during development. Acts as a multifunctional regulator of pathfinding that simultaneously mediates NELL2 repulsion, inhibits SLIT repulsion, and facilitates Netrin-1/NTN1 attraction. In spinal cord development plays a role in guiding commissural axons probably by preventing premature sensitivity to Slit proteins thus inhibiting Slit signaling through ROBO1/ROBO2. Binding OF NELL2 to the receptor ROBO3 promotes oligomerization of ROBO3, resulting in the repulsion of commissural axons in the midline. ROBO3 also indirectly boosts axon attraction to NTN1 without interacting with NTN1 itself (By similarity).
Synonyms: RBIG1; FLJ21044; HGPS; HGPPS; HGPPS1; RIG1
Tractability: Antibody: its Gene Ontology location is reachable by antibodies, with high confidence; UniProt predicts a signal peptide or a membrane-spanning region; the Human Protein Atlas places it where antibodies can reach. PROTAC: ubiquitination databases record sites on it.
Gene: Protein-coding gene on chromosome 11 (124,865,432 to 124,881,471, forward strand). Ensembl gene ENSG00000154134.
Subcellular location: Membrane
Subcellular location (Human Protein Atlas): Plasma membrane; Vesicles
Pathways (Reactome):
Developmental Biology: ROBO receptors bind AKAP5; Regulation of commissural axon pathfinding by SLIT and ROBO; Regulation of expression of SLITs and ROBOs
Gene Ontology:
Molecular function: protein binding; cell-cell adhesion mediator activity
Biological process: axon guidance; axon midline choice point recognition; dendrite self-avoidance; homophilic cell-cell adhesion; brain development; commissural neuron axon guidance; negative regulation of negative chemotaxis; positive regulation of axon guidance; positive regulation of axonogenesis; tube development
Cellular component: axon; membrane; plasma membrane
Genetic constraint (gnomAD): Loss-of-function variants: 96 observed, 151.79 expected, observed/expected ratio (o/e) 0.63, 90% interval 0.54 to 0.75. The upper end of that interval is the gene's LOEUF score, 0.75, which puts it in group 3 of 6, group 1 being the genes least tolerant of losing a copy. Missense variants: 1,854 observed, 1,794.2 expected, observed/expected ratio (o/e) 1.03, 90% interval 0.99 to 1.07. Synonymous variants: 778 observed, 722.27 expected, observed/expected ratio (o/e) 1.08, 90% interval 1.01 to 1.14.
Gene-disease validity (ClinGen):
ClinGen rates the evidence that ROBO3 causes each of these diseases.
gaze palsy, familial horizontal, with progressive scoliosis 1 (autosomal recessive): Definitive.
Homologues: Orthologues: chimpanzee ROBO3 (99% identical), macaque ROBO3 (97% identical), dog ROBO3 (90% identical), pig ROBO3 (90% identical), rabbit ROBO3 (88% identical), rat Robo3 (87% identical), mouse Robo3 (86% identical), guinea pig ROBO3 (86% identical), tropical clawed frog robo3 (53% identical), zebrafish robo3 (53% identical), zebrafish zgc:77784 (7% identical). Paralogues in human: ROBO2 (44% identical), ROBO1 (44% identical), SDK2 (18% identical), HMCN2 (18% identical), DCC (18% identical), NEO1 (17% identical), IGDCC4 (17% identical), MXRA5 (17% identical), SDK1 (17% identical), IGSF10 (16% identical), NRCAM (16% identical), CNTN3 (16% identical), and 24 more.
Diseases named in the same sentence as ROBO3 in open-access papers:
ROBO3 is named in the same sentence as 43 diseases in open-access papers, as found by Europe PMC text mining. Sharing a sentence is not in itself a finding about the gene and the disease. The quoted sentences say what the papers report.
horizontal gaze palsy with progressive scoliosis (9 papers, 2010 to 2025). "Other insults to the development of the VIth nerve include HGPPS (Horizontal Gaze Palsy with Progressive Scoliosis), in which it is mutations of the gene ROBO3, located at 11q23, which are responsible for the resulting phenotype." (PMID 25309358, 2014). "Horizontal gaze palsy with progressive scoliosis (HGPPS) is a rare autosomal recessive disease associated with mutation in the Roundabout-3 (ROBO3) gene (chromosome 11q23-25)." (PMID 40698216, 2025). "Mutations in ROBO3 cause horizontal gaze palsy with progressive scoliosis (HGPPS), which is a rare disorder that affects the spine and vision." (PMID 37962965, 2024). "Horizontal gaze palsy with progressive scoliosis (HGPPS) is a rare congenital disorder with autosomal recessive inheritance that is associated with mutations in the ROBO3 gene located at chromosome 11q23-25." (PMID 25885466, 2015). "Bi-allelic mutations in the Roundabout homolog of Drosophila 3 (ROBO3) gene cause horizontal gaze palsy with progressive scoliosis (HGPPS; OMIM 607313), a rare autosomal recessive disorder with oculomotor and general disturbances in innervation." (PMID 21850172, 2011). "Clinical and molecular characterization of patients with horizontal gaze palsy with progressive scoliosis (HGPPS) to extend existing knowledge of the phenotype caused by mutations in the Roundabout homolog of Drosophila 3 (ROBO3) gene." (PMID 21850172, 2011). "In humans, mutations in ROBO3 cause a rare syndrome called horizontal gaze palsy with progressive scoliosis (HGPPS)." (PMID 20231872, 2010). "CHL1 encodes an axon guidance protein related to Robo3, mutations of which could lead to horizontal gaze palsy with progressive scoliosis (HGPPS), a rare disease marked by severe scoliosis." (PMID 24512353, 2014). "Horizontal gaze palsy with progressive scoliosis (HGPPS) is an autosomal recessive disorder caused by mutations in the ROBO3 gene, resulting in a critical absence of crossing fibers in the brainstem." (PMID 25885466, 2015). "Moreover, some Cre;Robo3 lines represent potential models that can be used to study human syndromes, including horizontal gaze palsy with progressive scoliosis (HGPPS)." (PMID 20231872, 2010).
scoliosis (6 papers, 2020 to 2025). A congenital or acquired spinal deformity characterized by lateral curvature of the spine. "The child had typical findings of HGPPS, i.e., horizontal gaze palsy, scoliosis, and characteristic findings on MRI associated with homozygous c.575G>A (p.Gly192Asp) mutation in ROBO3 gene." (PMID 40698216, 2025). "Moreover, ROBO3 mutations are also thought to cause musculoskeletal changes during the development of scoliosis." (PMID 37861544, 2023). "The ROBO3 gene causes the simultaneous occurrence of scoliosis and visual disorders." (PMID 37861544, 2023). "However, the severe scoliosis that develops during childhood is less well understood and is thought to involve asynchronous muscle contractions, which underlie the breathing deficits in ROBO3 mutant mice as well as defects in axial motor control." (PMID 32580277, 2020). "Several genes encoding commissural axon guidance molecules, including ROBO3, EPHA4, CHL1, and DSCAM, are strongly associated with scoliosis." (PMID 37962965, 2024). "In fact, it is unclear if ROBO3 mutations alter ligand recognition, protein folding, or targeting and whether the resultant changes in protein function might have a differential effect on developing nerve fiber tract decussating and/or on clinical expression such as scoliosis." (PMID 32580277, 2020). "In fact, it is unclear if ROBO3 mutations alter ligand recognition, protein folding, or targeting and whether resultant changes in protein function might have a differential effect on developing nerve fiber tract decussating and/or on clinical expression such as scoliosis." (PMID 32580277, 2020). "Human ROBO3 mutations can lead to HGPPS, which is typically characterized by the congenital absence of horizontal gaze, progressive scoliosis, and failure of the corticospinal and somatosensory axon tracts to cross the midline in the medulla." (PMID 36186627, 2022).
pancreatic cancer (5 papers, 2020 to 2024). "In pancreatic cancer, ROBO3 was highly expressed in tumor specimens, and its overexpression promoted cellular growth and invasion in vivo and in vitro." (PMID 34881275, 2021). "Upregulation of Robo3 expression in the human pancreatic cancer cell lines PANC-1 and Capan-1 significantly promoted their growth and invasion in mice." (PMID 32670371, 2020). "We show that ROBO3 was highly expressed in a greater proportion of PDAC samples, particularly in pancreatic tumors with poor differentiation and a BL phenotype." (PMID 35993361, 2022). "Robo3, the inhibitor of Robo2, activates the WNT/β-catenin pathway, thus promoting pancreatic cancer growth and invasion." (PMID 32670371, 2020).
colorectal cancer (3 papers, 2015 to 2023). A primary or metastatic malignant neoplasm that affects the colon or rectum. "Instead of binding to Slit1-3, these changed residues now favour mammalian Robo3 forming a complex with the deleted in colorectal cancer (DCC) protein, a Netrin-1 receptor, to transduce Netrin-1 mediated attractive signaling." (PMID 28234971, 2017). "Instead of binding to Slit1-3, mammalian Robo3 forms a protein complex with the Netrin-1 receptor DCC (Deleted in Colorectal Cancer) through their cytoplasmic domain." (PMID 28234971, 2017). "Other pathways identified were Beta‐catenin‐dependent transcription regulation in colorectal cancer; Development_ROBO2, ROBO3, and ROBO4 signaling pathways, Notch signaling in oligodendrocyte precursor cell differentiation in multiple sclerosis and Signal transduction_mTORC1 upstream signaling." (PMID 36329628, 2023).
rheumatoid arthritis (3 papers, 2010 to 2023). A chronic, systemic autoimmune disorder characterized by inflammation in the synovial membranes and articular surfaces. "Compared with those in healthy individuals, the synovial fibroblast levels of ROBO3, pro-inflammatory cytokines, and cartilage degradation were significantly upregulated in patients with rheumatoid arthritis." (PMID 38035102, 2023). "Previous studies of our group detected significantly increased Robo3 expression in rheumatoid arthritis synovial fibroblasts (RASF) compared to SF and in melanoma cell lines compared to melanocytes (NHEM)." (PMID 27660555, 2016). "Recent studies demonstrated that Robo3 shows an altered expression in rheumatoid arthritis as well as in melanoma." (PMID 27660555, 2016). "Until today no detailed studies of the two Robo3 isoforms (Robo3A and Robo3B) and their roles in rheumatoid arthritis synovial fibroblasts, respectively malignant melanoma are available." (PMID 27660555, 2016).
breast carcinoma (2 papers, 2021 to 2022). "We identified ROBO3 as a gene consistently upregulated upon chemotherapy survival in the basal-like mammary carcinoma WAP-T mouse model." (PMID 36057630, 2022). "However, studies of ROBO/SLIT signaling in cancers are scarce and the implication of ROBO3 in mammary carcinoma is lacking so far." (PMID 36057630, 2022).
cervical cancer (2 papers, 2011 to 2014). A primary or metastatic malignant neoplasm involving the cervix. "Hypermethylation at the promoters of genes (SLIT1, SLIT2, SLIT3, ROBO1, and ROBO3) involved in Slit-Robo pathway resulting in down-regulated gene expression was also indentified in invasive cervical cancer." (PMID 22140553, 2011).
ischemic stroke (2 papers, 2015 to 2022). A stroke disorder caused by obstruction of blood flow to the brain, due to thrombotic (local blood clot formation) or embolic (due to a blood clot or other material traveling from another site) event. "Roundabout guidance receptor 3 (Robo3) is known to be associated with neuronal migration and is one of the key downregulated markers for the late-stage animal model of ischemic stroke." (PMID 35887140, 2022). "Only one report has identified ROBO3 mutation in HGPPS patients presenting with ischemic stroke symptoms on the ipsilateral side of the infarct." (PMID 25885466, 2015). "Only one report showed that HGPPS patients with ROBO3 mutations displayed ischemic stroke symptoms on the ipsilateral side of the infarct." (PMID 25885466, 2015).
leukemia (2 papers, 2019 to 2025). A malignant (clonal) hematologic disorder, involving hematopoietic stem cells and characterized by the presence of primitive or atypical myeloid or lymphoid cells in the bone marrow and the blood. "High expression levels of ROBO3 and ROBO4 RNA were noted in poor Cancer and Leukemia Group B (CALGB) cytogenetic risk group of patients in comparison with normal and favorable risk groups (p = 0.0029 and p = 0.0003, respectively, from ANOVA-Kruskall–Wallis test)." (PMID 30820596, 2019). "Four of these genes were reported for leukemias (IRS1, RUNX2, CCDC50 and ROBO3) and four others were reported to be involved in other types of cancers (NSG1, CAMK1D, CD3E, KLF8)." (PMID 41146244, 2025).
amelogenesis imperfecta type 3 (1 paper, 2016). "These include IHH involved in skeletal malformations, ROBO3 involved in horizontal gaze palsy with progressive scoliosis, PCSK9 involved in familial hypercholesterolemia, FAM83H related to amelogenesis imperfecta type 3 and GJA3 associated with congenital cataracts." (PMID 26861414, 2016).
Anosmia (1 paper, 2025). An inability to perceive odors. "It was molecularly proven in 25 (8 CHD7 mutations, 6 FGFR1 mutations, 7 ANOS1 mutations, 2 PROKR2 mutations, 1 digenic SOX10/SEMA3F mutation, and 1 digenic ROBO3/IGFS10 mutation with anosmia and later absent puberty)." (PMID 40193582, 2025).
congenital diaphragmatic hernia (1 paper, 2022). A posterolateral defect of the diaphragm that allows passage of abdominal viscera into the thorax, leading to respiratory insufficiency and persistent pulmonary hypertension with high mortality. "Three genes located at 11q24.2 region, ROBO3, ROBO4, and CDON, are possible candidate genes for congenital diaphragmatic hernia." (PMID 35440058, 2022).
epilepsy (1 paper, 2023). A brain disorder characterized by episodes of abnormally increased neuronal discharge resulting in transient episodes of sensory or motor neurological dysfunction, or psychic dysfunction. "In a lithium‐pyrrolizidinium chloride‐induced rat model of epilepsy, Robo3 expression in the hippocampus is found to decrease over time during acute and chronic epilepsy in epileptic rats." (PMID 38680506, 2023).
gaze palsy (1 paper, 2015). "Furthermore, homozygous mutations in ROBO3 have been identified as a cause of gaze palsy with progressive scoliosis (MIM 607313), a distinctly different phenotype to that described here, so this variant was again considered unlikely to be the pathogenic mutation in this family." (PMID 25928877, 2015).
hemorrhagic stroke (1 paper, 2015). A stroke caused by a bleed on the brain. "The present case is the first known report of hemorrhagic stroke with a confirmed ROBO3 mutation and uncrossed corticospinal tracts resulting in ipsilateral putaminal hemorrhage and hemiparesis." (PMID 25885466, 2015).
Intellectual disability (1 paper, 2021). "The lack of BRPF1 can also lead to multiple gene (such as Robo3 and Otx1) transcription reduction, the loss of neuronal migration and neural tube closure, the control of transcriptional regulation, and it can cause neurodevelopmental disorders, which can result in intellectual disability." (PMID 33643973, 2021).
intracranial hemorrhage (1 paper, 2015). Bleeding within the SKULL, including hemorrhages in the brain and the three membranes of MENINGES. "Two case reports have described patients with ipsilateral hemiplegia or hemiparesis caused by intracranial hemorrhage, but mutations in the ROBO3 gene were not examined in these cases." (PMID 25885466, 2015). "We report the first known HGPPS case with intracranial hemorrhage and ROBO3 mutation showing an absence of major crossing pathways by DTI." (PMID 25885466, 2015).
melanoma (1 paper, 2016). A malignant, usually aggressive tumor composed of atypical, neoplastic melanocytes. "Here, mRNA levels of the two Robo3 isoforms were determined in different melanoma cell lines." (PMID 27660555, 2016).
osteoporosis (1 paper, 2023). A condition of reduced bone mass, with decreased cortical thickness and a decrease in the number and size of the trabeculae of cancellous bone (but normal chemical composition), resulting in increased fracture incidence. "Of four key crosstalk genes (ARHGEF10, PCDH7, CST6, and ROBO3), PCDH7 was identified and validated as relating the development of both sarcopenia and osteoporosis." (PMID 37476411, 2023).
retinoblastoma (1 paper, 2010). A malignant tumor that originates in the nuclear layer of the retina. "Robo3, also called Rig-1 (retinoblastoma inhibiting gene 1), was isolated as the product of a gene up-regulated in retinoblastoma-deficient mice." (PMID 20231872, 2010).
Stroke (1 paper, 2022). Sudden impairment of blood flow to a part of the brain due to occlusion or rupture of an artery to the brain. "Using real-time RT-PCR of stroke brain tissues, we validated the expression of three selected neuronal genes from the network: Robo3, Lingo1, and NeuroD2, whose expression values were >2 in NPC-CM(M) than in NPC-CM(S)." (PMID 35887140, 2022).
systemic lupus erythematosus (1 paper, 2023). An autoimmune multi-organ disease typically associated with vasculopathy and autoantibody production. "This study demonstrated that the pathways related to systemic lupus erythematosus, chemokine signaling, and leukocyte transendothelial migration were significantly enriched in the high-ROBO3 expression group." (PMID 38035102, 2023). "In the validation set GSE7305, CXCL12, ROBO3, and SCG2 were significantly enriched in immune-related pathways, including cytokine-cytokine receptor interaction, chemokine signaling pathway, leukocyte transendothelial migration, systemic lupus erythematosus, and MAPK signaling pathway." (PMID 38035102, 2023).